MIF (macrophage migration inhibitory factor)
Diseases named in the same sentence as MIF in open-access papers (continued):
Sharing a sentence is not in itself a finding about the gene and the disease.
infection (185 papers, 2007 to 2026). The state of being infected such as from the introduction of a foreign agent such as serum, vaccine, antigenic substance or organism. "Reports indicate that mice deficient in MIF lack an effective innate immune response following infection with the Nippostrongylus brasiliensis." (PMID 38786064, 2024). "MIF has since been implicated in a multitude of innate and adaptive physiologic processes, particularly in response to infection and inflammation, and understanding of its role in tumorigenesis has expanded in recent years." (PMID 38732068, 2024). "Seven days post-Plasmodium yoelii 17XL infection, higher levels of IL-4, IL-10, IL-12, and IL-17 were observed in MIF-deficient mice than WT mice." (PMID 38275363, 2023). "The mesenteric lymph nodes of MIF-deficient mice also showed higher GATA3 expression seven days post-infection." (PMID 38275363, 2023). "Here, MIF-deficient mice exhibited a lower parasite load as well as lower IL-6 induction seven days after infection than WT specimens." (PMID 38275363, 2023). "While IFN-γ and IL-17 increased in WT mice during infection, they remained unchanged in MIF-deficient mice post-infection." (PMID 38275363, 2023). "On the other hand, BeWo cells naturally exhibit reduced expression of MIF, and this has been associated with higher susceptibility to infection by T. gondii." (PMID 36968102, 2023). "Conversely, MIF-deficient mice produced fewer proinflammatory cytokines, had more severe organ damage, and succumbed more rapidly to infection than WT mice." (PMID 38275363, 2023). "The levels of IFN-γ, IL-12, as well as TNF-α, were decreased in the post-infection phase in MIF-deficient mice compared with control mice." (PMID 38275363, 2023). "An opposite tendency was observed in the secretion of IL-4, which was increased in MIF-deficient mice after infection compared to WT mice." (PMID 38275363, 2023). "MIF-deficient BALB/c mice were unable to reduce worm burdens or egg output following a primary infection due to insufficient M2 polarization." (PMID 35215200, 2022). "We first examined if MIF deficiency altered the outcome of infection with the helminth parasite N. brasiliensis." (PMID 35288645, 2022). "They demonstrate that macrophage migration inhibitory factor (MIF) is needed for expansion of intestinal tuft cells during NB infection and that MIF-deficient mice show defective innate responses." (PMID 36430676, 2022). "MIF was also shown to affect pathologies, caused by infection of different parasites, such as bacteria, protozoa and viruses." (PMID 34662363, 2021). "The prevalence of high expression MIF alleles in different human populations is indicative of the important protective effect this cytokine plays in infections where loss of pathogen control produces lethality." (PMID 32244916, 2020). "The most impressive impact of vaccination against parasite MIF was shown in a study in which mice were immunized with a Plasmodium berghei MIF-encoding RNA vector prior to infection with blood or liver stage parasites." (PMID 32244916, 2020). "We noted a significant delay in peritoneal macrophage activation in MIF-deficient animals, with a lag also evident in production of these archetypal markers, although the effect was less obvious at the tissue site of infection." (PMID 31708913, 2019). "As MIF-deficient mice mounted a normal adaptive B- and T cell response to infection, we concluded that these mice must lack a key innate effector population, which we propose are the IL-4R-dependent M2 macrophages." (PMID 31708913, 2019). "Infection also results in activation of ILC2s to express IL-5 which is almost totally ablated in the MIF-deficient animals, within an overall reduction of ILCS in the MLN." (PMID 31708913, 2019). "Gene expression differences for Arl2bp and Phc2 were confirmed by RT-PCR on MLN samples at day 5 of infection of wild-type and MIF-deficient mice." (PMID 31708913, 2019).
infection (continued). "We further established the role of MIF in testing a pharmacological inhibitor, which recapitulated both impaired expression of M2 gene products, and greater susceptibility to infection, that are observed in the gene-targeted mice." (PMID 31708913, 2019). "Mice lacking STAT3 in their myeloid compartment were found to phenocopy the MIF-deficient mice in failing to reject a challenge infection of H. polygyrus." (PMID 31708913, 2019). "The MIF protein functions as a cytokine that promotes inflammatory processes in response to pathogenic infection." (PMID 29773680, 2018). "The experiments revealed that endothelial cell-expressed MIF participates in pro-atherosclerotic lesion formation caused by P. gingivalis ATCC 33277 infection." (PMID 29482504, 2018). "For example, the control of infection mediated by MIF is associated with increased systemic inflammation, tissue damage, and death." (PMID 29867817, 2018). "These experiments revealed that MIF in endothelial cells participates in the pro-atherosclerotic lesion formation caused by P. gingivalis ATCC 33277 infection." (PMID 29482504, 2018). "Consistent with this, MIF-deficient mice were more susceptible to infection with Salmonella typhimurium, producing lower levels of IL-12, IFN-γ, and TNF-α." (PMID 26617609, 2015). "The study also showed that in thyroid-deficient animals, the outcome from severe infection is worse than euthyroid animals, and that inhibition of MIF with the hormonally inactive D-isomer of T4 protects against mortality." (PMID 26318747, 2015). "Studies with MIF-deficient mice confirmed an upstream activating role for MIF in diverse inflammatory responses in the host response to infection and tumorigenesis." (PMID 25329068, 2014). "Since African trypanosomes trigger a persistent type I/M1 immune response in trypanosusceptible (e.g. T. brucei brucei (T. brucei)) infected mice, we evaluated the potential role of MIF in the development of infection-associated pathogenicity." (PMID 25255103, 2014). "In the present paper we discuss the role of MIF in the host-parasite interaction upon infection caused by protozoan parasites." (PMID 22496958, 2012). "Upon systemic infection with T. gondii, IFN-γ and TNF-α mediated responses are upregulated by MIF, and Mif−/− mice are more susceptible to infection presenting increased parasite burden." (PMID 21977228, 2011). "A MIF inhibitor administered during P. aeruginosa-induced infection ameliorated the disease-associated pathology." (PMID 20361053, 2010). "This increased bacterial burden in the reconstituted MIF KO correlated with elevated pathology scores, indicative of increased susceptibility to infection." (PMID 20361053, 2010). "Here, all MIF-deficient mice died within 25 days of per os infection." (PMID 38275363, 2023). "MIF is felt to contribute to detrimental inflammation but may be crucial in controlling infection caused by mycobacterial diseases." (PMID 36893126, 2023). "Another study showed that infection with Ross River virus leads to the production of macrophage migration inhibitory factor (MIF), which is associated with muscle damage, and that MIF-deficient mice are protected against muscle degeneration despite having similar viral titers." (PMID 36538023, 2023). "MIF expression is typically associated with infection or pathogenic inflammatory conditions." (PMID 36329091, 2022). "The elimination of bacteria from the spleen and liver was not affected by anti-MIF antibody (Ab) injection in the sublethal infection, whereas the same treatment does rescued mice from the lethal infection indicating that in case of lethal L. monocytogenes, MIF can act as a susceptibility factor." (PMID 35464430, 2022). "While in general infection-associated MIF promotes a pro-inflammatory response that may contribute to pathogen control, sustained inflammation can cause collateral tissue/organ damage." (PMID 35464430, 2022).
infection (continued). "One possible explanation for this is that high expression MIF alleles confer protection against infections, such as community-acquired pneumonia, which may be mechanistic triggers for SLE through antigenic mimicry." (PMID 26617609, 2015). "Our present findings represent the first evidence that enhanced MIF production is associated with progressive cardiac impairment in chronic human infection with T. cruzi, strengthening the relationship between inflammatory response and parasite-driven pathology." (PMID 23451183, 2013). "Hence, MIF deficiency both reduces pathology during infection and still allows for sufficient host responses to clear bacteria." (PMID 20361053, 2010). "MIF-deficient mice also show increased susceptibility to L. major, highlighting the important role of this cytokine in mounting an effective immune response to infection." (PMID 17645880, 2007). "Based on their data on MIF in regulating neonatal innate immune responses, the authors proposed that high levels of MIF in newborns might play a protective role to reduce susceptibility to infection during the neonatal period." (PMID 33673075, 2021). "Therefore, using MIF blocking Nbs at later stages of infection might be a novel way to attenuate T. congolense associated pathology and allow animals to remain productive." (PMID 32012211, 2020). "Thus, it is possible to speculate that MIF is secreted in response to infection, and it then associates with its receptor, signaling an intracellular pathway in response to infection." (PMID 31068920, 2019). "Furthermore, we also found that PMNs from MIF-deficient mice had a better innate ability to kill P. aeruginosa in an in vitro opsonic-killing assay, indicating a likely cellular basis for the better control of infection in thee animals." (PMID 20361053, 2010). "Cell-to-cell communication analysis further indicated that the interaction between the epithelial, vascular endothelial, pDCs, and fibroblast subsets, except for COL3A1 fibroblasts, was enhanced mainly via CD74/(COPA or MIF) receptor ligands after infection." (PMID 41843736, 2026). "Even with the similarity to the levels of the untreated control group (which only increased MIF after infection), stimulation with Strongyloides antigens appears to favor the secretion profile of IL‐4, IL‐6, and MIF in some conditions." (PMID 41399974, 2026). "IL-6 and MIF are typically elevated during infection and contribute to inflammation, but our findings suggest that their reduction does not impair parasite control in BeWo cells." (PMID 41415569, 2025). "Treatment with 50–100 mg/kg baicalin upregulated MIF protein level in the spleen compared to the infection group (p < 0.001)." (PMID 40427533, 2025). "It seems likely that suppression of the host cytokine MIF is essential to allowing the infection to disseminate beyond the gastrointestinal tract, and this will be important to test." (PMID 40141253, 2025). "Chemokines, including CXCL8, CCL20, and MIF, recruit immune cells, such as neutrophils, macrophages, and T cells, to sites of infection and inflammation and play critical roles in the immune response to pathogens (45, –, 48)." (PMID 41081505, 2025). "The regulation of infection by MIF is also observed in placental explants, where increased levels of this cytokine during the first trimester, as well as its stimulation in the third trimester, contribute to a reduction in T. gondii DNA content." (PMID 41011132, 2025). "MIF assists in cell recruitment to the site of infection, it can promote the polarisation of macrophages to M2 cells, it inhibits the suppression of immune responses by glucocorticoids and influences the release of immune mediators by macrophages." (PMID 40565065, 2025). "The impact of MIF is highly context-dependent, influenced by factors such as the specific pathogen, stage of infection, overall immunological environment, and affected organ." (PMID 41159021, 2025).
infection (continued). "MIF is highly produced by TSCYTs and TSSYNs in both conditions, but the infection with T. gondii induces significantly higher levels of this cytokine compared to the mock conditions, and infected TSSYNs also release more MIF when compared to TSCYTs." (PMID 38771057, 2024). "Alternatively, MIF can be secreted by a variety of cell types in response to tissue damage, infection, and other forms of stress, and has been shown to have pro-inflammatory and immune-regulatory effects." (PMID 39495793, 2024). "One interesting data is the increase of MIF in TSSYNs when compared to TSCYTs, especially after infection." (PMID 38771057, 2024). "MIF functions as a main proinflammatory cytokine and VSMC proliferation promoter, and MIF expression and secretion levels are elevated in fibroblasts, monocytes, and endothelial cells after infection or hypoxia." (PMID 38555425, 2024). "TNF-α, IFN-γ, IL-1β, IL-6, and MIF are pro-inflammatory molecules that activate immune cells and defend against infection." (PMID 38572322, 2024). "It should therefore be noted that the effect of MIF is context-dependent and varies depending on the pathogen, stage of infection, and general immunological milieu." (PMID 38275363, 2023). "This review aims to provide an overview of MIF’s role in different types of infections to illustrate the interaction pathways and potential clinical applications of the macrophage migration inhibitory factor and the D-dopachrome tautomerase." (PMID 38275363, 2023). "By exploring the nuanced role of MIF in infection, immunity, and disease progression, we can pave the way for a more refined and personalized approach to MIF-targeting drugs and their application in the diagnosis and treatment in infections." (PMID 38275363, 2023). "Several studies reported that MIF was clearly detectable in excretory/secretory products of the parasite, and the MIF was secreted by the parasite into host tissue and blood during infection." (PMID 36983058, 2023). "Overall, the role of MIF in bacterial infections is complex and depends on the type of bacteria and the stage of infection." (PMID 38275363, 2023). "Upon damage or infection, intracellular MIF can also interact with nitrogen permease regulator-like 3 (NLRP3) to facilitate the interaction between NLRP3 and vimentin, resulting in the release of IL1β." (PMID 38052787, 2023). "As far as we know, MIF promotes leukocyte migration and enrolment to inflammation and infection sites." (PMID 36747174, 2023). "The role of MIF in different types of infections is controversial, as it has either a protective function or a host damage-enhancing function depending on the pathogen." (PMID 38275363, 2023). "Wt mice had basal levels of MIF but after Py17XL infection it increased significantly on days 5 and 7 postinfection." (PMID 36093199, 2022). "When evaluating the role of MIF or IL-10 on the course of other infections it is clear from many reports that interfering with either MIF or IL-10 affects differentially the pathogen burden." (PMID 35464430, 2022). "Helminth secretion of MIF at the site of infection can also induce production of endogenous host MIF and lead to AP-1-mediated blocking of proinflammatory gene expression by binding of the transcription factor Jun activation domain-binding protein 1 (JAB1)." (PMID 35215200, 2022). "During infection with T. brucei, both Mif gene expression and MIF protein levels are upregulated during the acute phase of infection, whereafter both decline again following clearance of the first peak of parasitaemia (typically day 5-6 post infection)." (PMID 35464430, 2022). "This study not only further proved the gut microbiota changes in C57BL/6 mice caused by PbA infection, but also found that MIF deletion directly affected the changes in the gut microbiota of C57BL/6 mice before and after PbA infection." (PMID 36033889, 2022).
infection (continued). "Such MIF-mediated pathological side-effects during infection can be alleviated by pathogen-elicited IL-10 production." (PMID 35464430, 2022). "In this context, it was observed that MIF suppresses IL-10 production and down-regulates the serum cortisol level during a lethal infection with L. monocytogenes." (PMID 35464430, 2022). "In the context of HAT, a recent study conducted on Guinean HAT patients suggested that MIF expression is also increased during infection and coincides with pathology." (PMID 35464430, 2022). "Here we report that MIF is required for expansion of intestinal tuft cells during infection with the helminth Nippostrongylus brasiliensis." (PMID 35288645, 2022). "Here, it was shown that serum MIF levels increased during Py17XL infection in Wt mice, and this increase in MIF has also been documented in Plasmodium-infected patients." (PMID 36093199, 2022). "MIF is an upstream cytokine in the inflammatory cascade and is released upon stimulation by cellular stress, endotoxin, exotoxin, infection, inflammation, and immune responses." (PMID 35563296, 2022). "MIF is an important constituent of the host response to stress and infection and is the first mediator." (PMID 36389688, 2022). "Two weeks after AAV-shMIF infection, AAVs containing shRNA-resistant WT MIF or acetylation-mimicking MIF K78Q were injected into the cortex." (PMID 35585040, 2022). "Extrapolation of this physiological MIF/IL-10 model to other pathogens/infections deserves also some caution." (PMID 35464430, 2022). "In summary, this study further proved the gut microbiota changes in C57BL/6 mice caused by PbA infection and found that MIF deletion directly affected the changes in the gut microbiota of C57BL/6 mice before and after PbA infection." (PMID 36033889, 2022). "As immune cells are the primary sources of MIF secretion during infection, the formation and activation of lymphocytes, macrophages, and other immune cells in primary and secondary lymphoid organs play a key role in MIF expression." (PMID 35237527, 2021). "In the present study, the early expression of MIF and its time-dependent increase upon infection suggested a role of this cytokine in disease pathogenesis and progression." (PMID 35237527, 2021). "In general, during infection, matured lymphocytes (one of the predominant sources of MIF expression) migrate into the spleen to fight antigens." (PMID 35237527, 2021). "During infection, the MIF level is drastically elevated, which makes it possible to function as a biomarker for specific diseases." (PMID 35237527, 2021). "MIF is a pro-inflammatory cytokine that acts as a potential regulator of host response to infection." (PMID 35237527, 2021). "This implies that MIF cannot solely influence macrophage phenotype and is likely to act in tandem with other cytokines that are released during injury or infection to coordinate a pro-inflammatory response." (PMID 33853969, 2021). "In BeWo trophoblast cells, the infection induces macrophage migration inhibitory factor (MIF), IL-12 and IL-6 production, and in HTR-8/SVneo trophoblast cells, T. gondii infection also increases the IL-6 production." (PMID 33912151, 2021). "Among the many cytokines implicated in the immune response to Leishmania, the role of macrophage migration inhibitory factor (MIF) is particularly intriguing in that both the host and parasite produce their own orthologs during infection." (PMID 32244916, 2020). "We showed that MIF transcription was gradually increased at 12 h post-infection and peaked at 24 h post-infection in HuH-7 cells, while in another study, the MIF RNA level was only analyzed within 14 h post-infection." (PMID 32545679, 2020). "In this context, the MIF chemokine is present at high levels in the amniotic fluid of women in PTL with infection and its expression is increased in chorioamniotic membranes during infection." (PMID 32779889, 2020).